SNORD115-28 (small nucleolar RNA, C/D box 115-28)
Synonyms: HBII-52-28
Gene: Small nucleolar RNA gene on chromosome 15 (25,222,348 to 25,222,428, forward strand). Ensembl gene ENSG00000200801.
Gene Ontology:
Biological process: RNA processing
Cellular component: nucleolus
Homologues: Orthologues: chimpanzee SNORD115 (100% identical), macaque SNORD115 (89% identical). Paralogues in human: SNORD115-42 (89% identical), SNORD115-1 (88% identical), SNORD115-12 (88% identical), SNORD115-13 (88% identical), SNORD115-15 (88% identical), SNORD115-26 (88% identical), SNORD115-31 (88% identical), SNORD115-35 (88% identical), SNORD115-4 (88% identical), SNORD115-40 (88% identical), SNORD115-41 (88% identical), SNORD115-6 (88% identical), and 37 more.